APOE (apolipoprotein E)
Diseases named in the same sentence as APOE in open-access papers (continued):
Sharing a sentence is not in itself a finding about the gene and the disease.
atherosclerosis (continued). "In the present study, we used apoE knock-out mice on RC or HF diet as the animal model at early and advanced stage of atherosclerosis, which was identified by serum lipids level analysis and oil red O staining of frozen sections of mice aorta roots that was consistent with our previous results." (PMID 20040117, 2009). "The present study showed that intraperitoneal inoculation of MP, CP or the both microbes aggravated atherosclerosis induced by cholesterol-enriched-diet in apoE KO male mice, as measured by plaque height, % luminal obstruction, adventitial inflammation and amount of plaque area/internal surface." (PMID 19744321, 2009). "In this study we aimed to analyze whether CP and/or MP aggravates atherosclerosis induced by cholesterol-enriched diet in C57BL/6 apoE KO male mice." (PMID 19744321, 2009). "Of special interest is the studies showing that airway exposure to concentrated ambient particles and single wall carbon nanotubes can promote progression of the atherosclerosis process in apolipoprotein E knockout mice (apoE-/-) that develop plaques in blood vessels at early age." (PMID 19243580, 2009). "Extremely low salt intake also causes more long-term adverse effects, such as acceleration of atherosclerosis, as shown in a genetic model of atherosclerosis, the apoE−/−mouse: a low-salt diet stimulated the renin–angiotensin system and increased the size of atherosclerotic plaques in the aorta." (PMID 18535843, 2009). "Although older ApoE-/- mice may develop atherosclerosis of the coronary arteries, only a small proportion of these are found to display evidence of more advanced coronary artery disease, such as plaque rupture." (PMID 19416523, 2009). "The extent of atherosclerosis was low in aortic root sections of ApoE−/− mice administered vehicle." (PMID 18560532, 2008). "The data demonstrated that pre-treatment and perhaps co-administration of MSCs homozygous for ApoE ε3 and dexamethasone may represent a novel therapy for severe instances of AD, atherosclerosis and other ApoE-related diseases." (PMID 18823563, 2008). "The hypothesis of a linkage between changes of adhesion molecules/cofactors and atherosclerosis was tested further by suppression of aortic lesion formation in apoE−/− mice by expression of very low levels of transgenic apolipoprotein E." (PMID 18560564, 2008). "Therefore, in the work reported here, we examined the effect of genetic deletion of TLR2 on the progression of atherosclerosis driven by a high fat diet and/or P. g infection in the ApoE+/− murine model." (PMID 18787704, 2008). "ApoE plays a key role in regulating cholesterol metabolism and atherosclerosis progression." (PMID 18464897, 2008). "Because these modifications have been related to cardiovascular diseases, we evaluated whether repeated exposure to SWCNTs (20 μg/mouse once every other week for 8 weeks) stimulates the progression of atherosclerosis in ApoE−/− transgenic mice." (PMID 17431486, 2007). "The relevance of TLR function in atherosclerosis is supported by the observation that a deletion of the MyD88 gene, encoding a pivotal adaptor molecule in the TLR signalling pathway, inhibits atherosclerosis in apoE-/- mice." (PMID 17980027, 2007). "Furthermore, it has been shown that increasing the numbers of Treg in atherosclerosis prone (ApoE-/-) mice by means of adoptive transfer leads to smaller atherosclerotic lesions, implicating that Treg do appear capable modifying plaque volume in vivo." (PMID 17712427, 2007). "Because these types of oxidative modifications are considered to play a role in atherogenesis, we further evaluated the effects of SWCNT respiratory exposure on atherosclerosis progression in ApoE−/− transgenic mice, a widely used model of human atherosclerosis." (PMID 17431486, 2007).
atherosclerosis (continued). "Elevated blood levels of IL-lβ and IL-6 increase the risk of type 2 diabetes, and lack of IL-lβ decreases the severity of atherosclerosis in ApoE-deficient mice on the C57B1/6 background, a model that develops insulin resistance when fed a Western diet." (PMID 16787541, 2006). "We tested if glucosamine affects atherosclerosis development in apoE-null mice." (PMID 16207378, 2005). "A study in hypercholesterolemic apolipoprotein E-deficient mice demonstrated that immunization with syngeneic apoptotic thymocytes, a process mimicking ECP, induced the production of IgM antibodies against oxidized low-density lipoproteins (OxLDL) that attenuated atherosclerosis." (PMID 41694367, 2026). "Finally, comparative analysis between these scRNAseq data sets and with our in-house HFD ApoE-/- atherosclerosis mouse model bulk RNA-seq data set was used to identify a novel MØ-specific STAT1-dependent integrated gene signature to monitor human atherosclerotic plaque formation." (PMID 40607379, 2025). "Furthermore, an ApoE/miR-155 double KO mouse model provided significant insights into the complex interplay among obesity, atherosclerosis, and non-alcoholic fatty liver disease (NAFLD), where, despite increased adipogenesis, these mice showed a reduction in atherosclerotic lesions." (PMID 40565538, 2025). "Therefore, AEP is required for HFD-induced atherosclerosis in APOE–/– mice." (PMID 40371638, 2025). "Notably, we constructed vascular endothelial cell‐specific GRK2 knockout mice on an ApoE‐/‐ background to investigate whether vascular endothelial cell‐specific knockout of GRK2 could alleviate the development of atherosclerosis." (PMID 40492401, 2025). "Considering that there is a positive correlation between circ‐PIAS1‐5 expression in the plasma and aorta of ApoE−/− mice fed a high‐methionine diet, we further elucidated whether circ‐PIAS1‐5 can be used as a novel diagnostic biomarker for HHcy‐associated atherosclerosis." (PMID 40089857, 2025). "In our study, by using the ApoE-KO mouse model, we showed that KMUP-1 could potentially be used as a therapeutic intervention in the prevention of cardiac dysfunction associated with rapidly developing atherosclerosis." (PMID 41194853, 2025). "Additionally, we explore the role of PDH in mediating Hcy-induced atherosclerosis in ApoE–/– mice." (PMID 39980347, 2025). "Activation studies of other platelet receptors such as P-selectin and phosphatidylserine, and measurement of platelet thromboxane B2 may further elucidate the state of platelet activation in ApoE−/−P-Jak2 KO mice and its contribution to the increase in atherosclerosis." (PMID 40825505, 2025). "However, prior efforts using AAV-PCSK9 in immunodeficient humanized NSG mice failed to generate significant atherosclerosis, likely due to insufficient cholesterol elevation (approximately 500 mg/dL vs approximately 1500 mg/dL in the apoE−/− model)." (PMID 40237461, 2025). "Furthermore, we used an atherosclerosis model using ApoE−/− mice to confirm whether EcN/PCSK9nb alleviated the phenotypes associated with atherosclerosis." (PMID 41244340, 2025). "Similarly, Indole-3-carbinol (I3C) inhibits atherosclerosis in ApoE-/- mice." (PMID 40356907, 2025). "In Western diet (WD)-fed Sphk1−/− mice and Sphk2−/− mice, both with an ApoE-deficient background, the exacerbation of atherosclerosis in mice lacking Sphk2, but not Sphk1, was attributed to impaired autophagic degradation of lipid droplets (LDs) in macrophages." (PMID 39920588, 2025).
atherosclerosis (continued). "As these observations were made in ApoE−/− mice on a normal chow diet, these observations could support the involvement of resident macrophages and mesenchymal cells in the early developmental stages of atherosclerosis." (PMID 40497946, 2025). "Furthermore, MCU inhibitors alleviate Western diet-induced atherosclerosis in ApoE-/- mice." (PMID 41329250, 2025). "While MMD is distinct from typical atherosclerosis, an APOE ε4‐driven propensity toward more atherogenic lipoprotein subclasses could conceivably intersect with the unique vascular milieu of MMD, exacerbating endothelial dysfunction and pathological neovascularization." (PMID 40365738, 2025). "In vivo studies in apolipoprotein E (apoE) knockout mice revealed that PCSK9 silencing could inhibit the progression of atherosclerosis by reducing vascular inflammation and limiting activation of the TLR4/NF-κB signaling pathway without changing plasma cholesterol levels." (PMID 41368357, 2025). "Thus, elucidation of other signaling pathways in platelets may further clarify the proinflammatory state and accelerated atherosclerosis that we report in ApoE−/−P-Jak2 KO mice." (PMID 40825505, 2025). "The use of diabetic ApoE−/− mice, while relevant, may not fully recapitulate the complex environment of human diabetes-associated atherosclerosis." (PMID 41083981, 2025). "Therefore, ApoE−/− mice fed a HFD were selected to study the anti-atherosclerosis mechanism of FDT." (PMID 38794213, 2024). "To test this hypothesis and investigate the role of IL1RAP in atherosclerosis, we treated apolipoprotein E–deficient (Apoe−/−) mice with a non-depleting IL1RAP-blocking antibody." (PMID 38563353, 2024). "In addition, apoE-deficient female mice lacking AR developed diet-induced obesity, dyslipidemia, and atherosclerosis." (PMID 39225098, 2024). "Apolipoprotein E -deficient (ApoE-/-) mice lacking both TLR4 or MyD88 show reduced atherosclerosis." (PMID 39399488, 2024). "Furthermore, the enhancement of femoral atherosclerosis induced by balloon injury in apoE KO rabbits further indicates that regardless of the methods used, increased atherosclerosis was consistently observed in the context of apoE deficiency." (PMID 39087075, 2024). "They then generated apoE-deficient mice with myeloid-specific inactivation of IL-10 and demonstrated that these mice exhibit a pro-inflammatory state, with significantly increased expression of TNF-ɑ, and CCL2, a chemokine linked to atherosclerosis as well as a trend toward increased IL-1β." (PMID 39062180, 2024). "Transgenic expression of LL-37 in apoE−/− mice increased aortic atherosclerosis further supporting its detrimental role in ASCVD." (PMID 39170950, 2024). "The enhancement of atherosclerosis in apoE KO rabbits may involve several mechanisms." (PMID 39087075, 2024). "In apolipoprotein E-deficient (ApoE−/−) mice fed with a high-fat (HF) diet, the beneficial effects and mechanism of exenatide on stress-related vascular senescence and atherosclerosis were investigated by using non-stressed as well as immobilized-stress in mice." (PMID 38892417, 2024). "To explore the potential effects of miR166a-3p derived from CDNVs in ApoE-/- mice fed a high-fat diet, we developed in vivo miR166a-3p mimics (agomiR166a-3p) and inhibitors (antagomiR166a-3p), and assessed their effects on body weight, lipid metabolism, inflammation, and atherosclerosis (AS)." (PMID 38475787, 2024). "Moreover, IMD can reduce the levels of fasting blood glucose (FBG), insulin, free fatty acid, triglycerides, and total cholesterol, thereby improving metabolic syndromes like obesity and insulin resistance in T1DM rats, T2DM mice, hyperhomocysteinemia mice, and ApoE−/− atherosclerosis mice." (PMID 39338366, 2024).
atherosclerosis (continued). "In this study, we examined whether p190RhoGEF over-expression in macrophages affects the atherosclerotic disease process in a mouse model: p190RhoGEF-TG mice were cross-bred with atherosclerosis-prone ApoE−/− mice to obtain p190RhoGEF-TG mice with an ApoE−/− background (TG/ApoE−/−)." (PMID 37628966, 2023). "The difference in plaque severity and composition between apoE−/− mice and rats is not yet fully understood but could be explained by species differences or by the background strain of the rats, which may be more resistant to atherosclerosis." (PMID 38079017, 2023). "Moreover, perivascular application of MI-2 significantly reduced atherosclerosis in carotid arteries of ApoE−/− mice fed a high-fat diet, suggesting that induction of ferroptosis in vascular SMCs inhibits neointima formation and the early development of atherosclerosis." (PMID 38097554, 2023). "To investigate the cellular and molecular mechanisms by which PDGFD regulates atherosclerosis development and CAD risk we developed a mouse atherosclerosis model that provided constitutive knockout of Pdgfd, as well as SMC-specific lineage marking in the ApoE−/−, C57BL/6 background." (PMID 36792607, 2023). "The similar lipid protein profile between HIVposEVs- and HIVnegEVs-treated apoE−/− mice (with different atherosclerosis burdens) also suggests that cholesterol levels are not a determining factor for the increased atherogenesis associated with HIVposEVs injection in apoE−/− mice." (PMID 37108729, 2023). "In addition, hydralazine decreased atherosclerosis in ApoE−/− mice fed a normal diet." (PMID 37958938, 2023). "We found that the twelve weeks of swimming training improved glucose tolerance, reduced visceral lipid accumulation, alleviated liver damage, and inhibited atherosclerosis progression in both obese WT mice and ApoE-/- mice, which could be partially blocked by EV biogenesis repression." (PMID 37191422, 2023). "However, our studies in experimental animal models of human diseases, e.g., an ApoE−/− mouse model of atherosclerosis, type II diabetic mice (db/db), and other animal models by other investigators described throughout this review, have shown that D-PDMP decreases LacCer synthase activity." (PMID 38203654, 2023). "In addition to atherosclerosis, high-fat diet fed ApoE-/- mice have been shown to be a model of non-alcoholic steatohepatitis (NASH) with hepatic fibrosis, a condition which is associated with an increased risk of postoperative death following major surgery in humans." (PMID 37033482, 2023). "Moreover, genetic iNOS deletion was found to minimize atherosclerosis in ApoE-KO mice in vivo." (PMID 37371915, 2023). "Additionally, APOE‐associated SNPs dominated our MWAS analysis, which could be attributed to the known association of ApoE with dyslipidemia and atherosclerosis." (PMID 36326588, 2023).
atherosclerosis (continued). "However, animal experimentation results indicate that after receiving whole spleen B cell transplantation, mice with splenectomy and apolipoprotein E knockout (ApoE−/−) exhibited significantly reduced aortic root atherosclerotic plaques, showing a protective role of B cells in atherosclerosis." (PMID 38221996, 2023). "Furthermore, an increased serum TMAO concentration was associated with a greater expression of CD36 (a renowned scavenger receptor) in the macrophages, which led to the internalization of lipids, the formation of foam cells, and the development of atherosclerosis in ApoE −/− mice." (PMID 36830968, 2023). "Finally, lymphatic dysfunction in ApoE−/− mice may also facilitate the progression of atherosclerosis by interfering with the efficiency of reverse cholesterol transport, an atheroprotective mechanism dependent on lymphatic transport." (PMID 36685213, 2022). "In contrast, treatment of ApoE−/− mice with human rIL-35 increased circulating and local Treg levels, inhibited the Th17 immune response, and reduced plaque size, suggesting that IL-35 alters the Th17/Treg balance by upregulating Treg immune responses, thereby attenuating atherosclerosis." (PMID 36211578, 2022). "Finally, we used male ApoE−/− mice and induced a severe atherosclerosis model fed with HCD." (PMID 35842658, 2022). "However, despite this seemingly atheroprotective function, EC-specific SR-B1 KO mice generated on an ApoE KO background showed a marked reduction of atherosclerosis in both males and females in both mixed and C57BL/6 background, while plasma TC, TG, HDL, and lipoprotein profiles were unaltered." (PMID 35332444, 2022). "Furthermore, it was reported that transgenic introduction of human sclerostin could inhibit inflammatory cytokines and chemokines, while prevent AA and atherosclerosis progression in ApoE-/- mice with AngII infusion." (PMID 35966595, 2022). "Therefore, the ApoE−/− and Fas−/− double knockout B6 mouse models on high fat diet, as we established here, exhibit both atherosclerosis and lupus-like manifestations and are more suitable for studying the pathogenesis and treatment of accelerated atherosclerosis in SLE." (PMID 35850768, 2022). "Indeed, the mechanistic link between atherosclerosis and neuroinflammation has barely been addressed so far, except in one experimental study on the animal model of atherosclerosis: the ApoE-knockout (ApoE-/-) adult mouse fed for 2 months with a hyperlipidic diet." (PMID 35663580, 2022). "In addition, the limitations of the ApoE-/- animal model, and animal models of atherosclerosis in general, in accurately replicating the complexity of severe human atherosclerosis as well as the potential occurrence of gender-specific epigenetic alterations should be considered." (PMID 36552592, 2022). "However, data from the current study support the hypothesis that the modulation of endothelial pyroptosis involves the inhibition of atherosclerosis by SAA in ApoE−/− mice with STZ-induced diabetes." (PMID 36425580, 2022). "Paradoxically, it is likely that testosterone deficiency in male agouti KKAy+/–ApoE–/– may be responsible for accelerated atherosclerosis vs. non-agouti genotypes." (PMID 36505365, 2022). "Interestingly, coronary atherosclerosis does not develop in ApoE-deficient mice (a popular animal model of atherosclerosis), although the anatomy of their coronary arteries is not fundamentally different from that in humans." (PMID 35163667, 2022). "Moreover, the deletion of PGRN exacerbated atherosclerosis in ApoE knockout mice through the promotion of inflammation, accumulation of excessive cholesterol in macrophages and altered activity and amount of HDL-associated protein demonstrates the anti-atherogenic effect of PGRN." (PMID 35453521, 2022).